OR4M2B (olfactory receptor family 4 subfamily M member 2B)
Description:
Odorant receptor.
Gene: Protein-coding gene on chromosome 15 (21,637,909 to 21,638,992, forward strand). Ensembl gene ENSG00000182974.
Subcellular location: Membrane
Gene Ontology:
Molecular function: olfactory receptor activity; G protein-coupled receptor activity
Biological process: detection of chemical stimulus involved in sensory perception of smell; G protein-coupled receptor signaling pathway
Cellular component: plasma membrane; membrane
Genetic constraint (gnomAD): Loss-of-function variants: 1 observed, 1.58 expected, observed/expected ratio (o/e) 0.63, 90% interval 0.2 to 1.82. That is too few expected variants to judge how well the gene tolerates losing a copy. Missense variants: 18 observed, 29.13 expected, observed/expected ratio (o/e) 0.62, 90% interval 0.43 to 0.92. Synonymous variants: 7 observed, 8.57 expected, observed/expected ratio (o/e) 0.82, 90% interval 0.46 to 1.51.
Homologues: Orthologues: macaque OR4M1 (93% identical), rat Or4m1 (88% identical), mouse Or4m1 (88% identical). Paralogues in human: OR4M2 (99% identical), OR4M1 (93% identical), OR4N5 (56% identical), OR4N2 (53% identical), OR4N4C (52% identical), OR4N4 (51% identical), OR4K1 (48% identical), OR4Q3 (48% identical), OR4K15 (47% identical), OR4E2 (47% identical), OR4S1 (47% identical), OR4D5 (47% identical), and 116 more.
Diseases named in the same sentence as OR4M2B in open-access papers:
OR4M2B is named in the same sentence as 1 disease in open-access papers, as found by Europe PMC text mining. Sharing a sentence is not in itself a finding about the gene and the disease.
OR4M2B shares sentences with these, for which no sentence is quoted: dengue (1 paper).